KCNJ1 (potassium inwardly rectifying channel subfamily J member 1)
Description:
Inward rectifier potassium channels are characterized by a greater tendency to allow potassium to flow into the cell rather than out of it. Their voltage dependence is regulated by the concentration of extracellular potassium; as external potassium is raised, the voltage range of the channel opening shifts to more positive voltages. The inward rectification is mainly due to the blockage of outward current by internal magnesium. This channel is activated by internal ATP and can be blocked by external barium. In the kidney, probably plays a major role in potassium homeostasis.
Synonyms: ROMK1; Kir1.1; ROMK
Tractability: Small molecule: a high-quality ligand is known; it belongs to a druggable protein family. Antibody: UniProt places it where antibodies can reach, with high confidence; its Gene Ontology location is reachable by antibodies, with high confidence; UniProt predicts a signal peptide or a membrane-spanning region. PROTAC: a small molecule that binds it is known.
Target class: Inwardly rectifying potassium channel; Potassium channels; Voltage-gated ion channel; Ion channel
Chemical probes: CHEMBL2441437, CHEMBL3612810 (high quality), ML111 (high quality), VU591
Safety:
Unwanted effects reported when the protein is acted on. In parentheses: how it was acted on, where the effect was seen, and who reports it.
Diabetes Mellitus (source: ClinPGx)
Increased Mortality (source: AOP-Wiki)
Gene: Protein-coding gene on chromosome 11 (128,836,315 to 128,874,671, reverse strand). Ensembl gene ENSG00000151704.
Subcellular location: Cell membrane
Pathways (Reactome):
Neuronal System: Potassium transport channels
Gene Ontology:
Molecular function: inward rectifier potassium channel activity; phosphatidylinositol-4,5-bisphosphate binding; potassium channel activity; protein binding; ATP binding
Biological process: gene expression; monoatomic ion transport; potassium ion import across plasma membrane; potassium ion transport; regulation of monoatomic ion transmembrane transport
Cellular component: cell surface; plasma membrane; membrane
Genetic constraint (gnomAD): Loss-of-function variants: 24 observed, 22.92 expected, observed/expected ratio (o/e) 1.05, 90% interval 0.76 to 1.47. The upper end of that interval is the gene's LOEUF score, 1.47, which puts it in group 6 of 6, group 1 being the genes least tolerant of losing a copy. Missense variants: 457 observed, 480.69 expected, observed/expected ratio (o/e) 0.95, 90% interval 0.88 to 1.03. Synonymous variants: 152 observed, 171.33 expected, observed/expected ratio (o/e) 0.89, 90% interval 0.78 to 1.01.
Gene-disease validity (ClinGen):
ClinGen rates the evidence that KCNJ1 causes each of these diseases.
Bartter disease type 2 (autosomal recessive): Definitive.
Homologues: Orthologues: chimpanzee KCNJ1 (99% identical), macaque KCNJ1 (98% identical), dog KCNJ1 (96% identical), pig KCNJ1 (95% identical), rabbit KCNJ1 (94% identical), mouse Kcnj1 (93% identical), rat Kcnj1 (93% identical), guinea pig KCNJ1 (90% identical), tropical clawed frog kcnj1 (84% identical), zebrafish kcnj1b (58% identical), zebrafish kcnj1a.1 (55% identical), zebrafish kcnj1a.6 (55% identical), and 10 more. Paralogues in human: KCNJ10 (47% identical), KCNJ15 (45% identical), KCNJ12 (44% identical), KCNJ18 (44% identical), KCNJ4 (44% identical), KCNJ2 (43% identical), KCNJ5 (42% identical), KCNJ6 (41% identical), KCNJ3 (41% identical), KCNJ11 (40% identical), KCNJ9 (40% identical), KCNJ8 (40% identical), and 3 more.
Diseases named in the same sentence as KCNJ1 in open-access papers:
KCNJ1 is named in the same sentence as 77 diseases in open-access papers, as found by Europe PMC text mining. Sharing a sentence is not in itself a finding about the gene and the disease. The quoted sentences say what the papers report.
Bartter syndrome (33 papers, 2013 to 2025). "Loss of function mutations in SLC12A1 or KCNJ1 in humans causes Bartter syndrome, which is characterized by hypokalemia, metabolic alkalosis (body pH elevation), polyuria (excess urination), salt wasting, hypercalciuria, and hypotension." (PMID 38195585, 2024). "Over 40 Bartter syndrome-associated mutations in KCNJ1 have been identified, yet their molecular defects are mostly uncharacterized." (PMID 37956218, 2023). "Subsequent genetic testing revealed that the infant carried two mutations in the KCNJ1 gene, E151K and a deletion of amino acids 116–119, which again strongly supports a diagnosis of antenatal Bartter syndrome." (PMID 37956218, 2023). "This region contains the ROMK gene that encodes the KCNJ1 potassium channel and is mutated in Bartter’s syndrome (type 2), a monogenic hypertension disorder." (PMID 37895212, 2023). "We are aware of a single case of transient Bartter syndrome in a preterm patient who was compound heterozygous for pathogenic variants in the KCNJ1 gene: a paternally inherited Arg338Stop variant and a maternally inherited Met357Thr variant." (PMID 32590952, 2020). "A gene panel associated with Bartter syndrome (including KCNJ1, AP2S1, CASR, GNA11, SLC12A1, and SLC12A3) was performed at a commercial lab (Prevention Genetics, Marshfield, Wisconsin, USA)." (PMID 32590952, 2020). "Loss-of-function mutations in ROMK (KCNJ1, the outward potassium channel) are associated with Bartter's syndrome, and ROMK inhibitors are used in the treatment of hypertension." (PMID 25785607, 2015). "Other syndromic variants of AI, particularly those involving mutations in SLC12A1 or KCNJ1, may present clinical features similar to Bartter syndrome and can progress more rapidly toward ESRD." (PMID 41427162, 2025). "KCNJ1 participated in potassium balance, and its mutation was able to trigger Bartter syndrome." (PMID 38440732, 2024). "For example, individuals carrying two defective copies of the gene encoding ROMK, KCNJ1, present with Type II Bartter syndrome, a life-threatening salt-wasting disorder in which children fail to thrive and are afflicted with a range of metabolic, renal, and neurological disorders." (PMID 32251469, 2020). "Here we describe another patient with compound heterozygous variants in the KCNJ1 gene, who exhibited the features of neonatal Bartter syndrome but showed spontaneous resolution of electrolyte abnormalities by 3 months of age while continuing to have polyuria and hypercalciuria." (PMID 32590952, 2020). "Bartter syndrome, encompassing types 1–3, stems from mutations in genes such as NKCC2 (SLC12A1), ROMK (KCNJ1), or CIC-Kb (CLCNKB), culminating in hypokalemic alkalosis and hypercalciuria." (PMID 40126616, 2025). "Whole-exome sequencing (WES) excluded pathogenic variants in renal tubulopathy genes including SLC12A3 (Gitelman syndrome), SLC12A1, CLCNKB, BSND, KCNJ1, MAGED2 (Bartter syndrome), and CASR, CLCNKA, KCNJ10 (hypokalemia-associated genes)." (PMID 40893942, 2025). "Type II of BS, also known as neonatal Bartter syndrome, is caused by loss-of-function mutations in the KCNJ1 gene, which codes for the apical inwardly rectifying potassium channel ROMK." (PMID 39273282, 2024). "Bartter syndrome is classified into five major genotypes caused by mutations in different genes, namely SLC12A1, KCNJ1, CLCNKB, CLCNKA, BSND, and MAGED2." (PMID 38238844, 2024). "Bartter syndrome is caused by mutations in SLC12A1 encoding NKCC2 (type I), KCNJ1 encoding ROMK (type II), CLCNKB encoding ClC‐Kb (type III) or BSDN encoding Barttin (type IV) (OMIM: 601678, 241200, 607364 and 602522, respectively)." (PMID 32603001, 2021). "Other causes of BS include mutations in the potassium voltage-gated channel subfamily J member 1 (KCNJ1) for Type II BS, chloride channel Kb (ClC-Kb) for Type III BS, Bartter syndrome, infantile, with sensorineural deafness (BSND) for Type IV BS, and calcium-sensing receptor (CaSR) for Type V BS." (PMID 31165006, 2019).
Hypokalemia (21 papers, 2007 to 2026). An abnormally decreased potassium concentration in the blood. "Furthermore, the lack of association between GHD and antenatal BS, which is caused by mutations in either the SLC12A1 (type I BS) or KCNJ1 (type II BS) gene, can be explained by the observation that the correction of hypokalemia is generally easier in antenatal BS than in classic BS." (PMID 24377430, 2013). "KCNJ1 mutations, encoding the ROMK potassium channel, often display transient hyperkalaemia in the neonatal period prior to development of classic hypokalaemia." (PMID 31935940, 2020). "It has been also suggested that the tubulopathy in RMS may resemble Bartter syndrome type II, where KCNJ1 mutations cause ROMK channel dysfunction, leading to hyperreninemia, hyperaldosteronism, hypokalaemia, hypercalciuria and nephrocalcinosis." (PMID 40241988, 2025).
Hypertension (17 papers, 2009 to 2025). The presence of chronic increased pressure in the systemic arterial system. "Carriers of single heterozygous pathogenic variants in SLC12A1, SLC12A3, and KCNJ1 were shown to have a reduced prevalence of hypertension and for SLC12A3 also in lower serum potassium levels." (PMID 37612755, 2023). "In contrast, individuals with only one mutated copy of KCNJ1 have a lower risk of hypertension and decreased blood pressure." (PMID 32251469, 2020). "Subsequently, researchers found that genetic variation in KCNJ1 is associated with lower blood pressure and that ROMK may be a potential therapeutic target for hypertension." (PMID 40332433, 2025). "Additionally, p.E151K, p.Y314C, p.T191N, p.E284Q, rs675759, rs675388, rs2846679, rs2855800, and rs2186832 in the KCNJ1 gene are observed to associate with blood pressure or hypertension." (PMID 36305246, 2022). "Haplotype analysis of the candidate genes KCNJ1, NEDD4L, BDKRB2, and CACNA1C was performed to investigate the potential associations with hypertension." (PMID 39859138, 2025).
Hyperkalemia (14 papers, 2015 to 2025). An abnormally increased potassium concentration in the blood. "Type II results from KCNJ1 gene mutation involving neonatal population with polyhydramnios, nephrocalcinosis, hypokalemic alkalosis, hyposthenuria, and transient hyperkalemia." (PMID 40666068, 2025).
Hypercalciuria (5 papers, 2021 to 2025). "For example, mutations in six of the amelogenesis imperfecta-associated genes (CLDN16, CLDN19, FAM20A, KCNJ1, SLC4A1, and WDR72) are associated with nephrocalcinosis, hypercalciuria, and renal failure." (PMID 33672174, 2021).
nephrocalcinosis (4 papers, 2021 to 2025). Nephrocalcinosis is a disorder that occurs when too much calcium is deposited in the kidneys. "One adult male patient initially presented with an incidental finding of nephrocalcinosis was diagnosed as a late-onset BS due to detection of a homozygous KCNJ1 missense mutation." (PMID 35761198, 2022).
Gitelman syndrome (2 papers, 2018 to 2025). Gitelman syndrome (GS), also referred to as familial hypokalemia-hypomagnesemia, is characterized by hypokalemic metabolic alkalosis in combination with significant hypomagnesemia and low urinary calcium excretion. "Loss-of-function mutations in SLC12A3, SLC12A1, and KCNJ1 genes, essential for normal renal NaCl reabsorption, cause Bartter’s and Gitelman’s syndromes." (PMID 29495593, 2018).
nephrolithiasis (2 papers, 2021 to 2022). The presence of a calculus in the pelvis of the kidney; this is most often composed of mineral salts and proteins. "In the present study, the proband, a ten-year old boy primarily incidentally detected with bilateral nephrolithiasis was found with compound heterozygous mutations of KCNJ1 gene by NGS." (PMID 35761198, 2022).
angiosarcoma (1 paper, 2016). A malignant tumor arising from the endothelial cells of the blood vessels. "Notably, expression of several potassium channels is modified in bladder cancer vessels vs controls (KCNC4, KCNG4, KCNS2) and in angiosarcoma vs controls (namely KCNJ16, KCNQ2, KCNJ15, KCNJ12, KCNJ1)." (PMID 27716384, 2016).
colorectal adenoma (1 paper, 2023). An adenoma that arises from the colon or rectum. "We studied the relationship between calcium reabsorption genes SLC12A1, KCNJ1 and SLC8A1 and colorectal adenomas." (PMID 37074453, 2023).
Down syndrome (1 paper, 2023). "Similar results were reported in a retrospective study from Finland where five cases with Down syndrome were identified in a cohort of 238 individuals, one of them with a pathogenic heterozygous KCNJ1 variant." (PMID 37065762, 2023).
gallstones (1 paper, 2025). Solid crystalline precipitates in the biliary tract, usually formed in the gallbladder, resulting in the condition of cholelithiasis. "New missense and nonsense mutations in both SLC12A1 and KCNJ1 genes associated with the risk of gallstone formation at an early age have been identified." (PMID 40149408, 2025).
Hyponatremia (1 paper, 2020). An abnormally decreased sodium concentration in the blood. "Transient neonatal hyponatremia warrants a multi-system workup and genetic variants of KCNJ1 should be considered." (PMID 32590952, 2020).
vitreoretinal degeneration (1 paper, 2013). "The Kcnj13 gene encodes a member of the inwardly rectifying potassium channel family of proteins and regulates ion transmembrane transport and mutations in Kcnj1 are associated with snowflake vitreoretinal degeneration." (PMID 23421592, 2013).
tumor (5 papers, 2013 to 2022). "Beyond that, 2 genes (AQP2, KCNJ1) were selected to analyze their relationship with tumor expression and clinical stage." (PMID 36313709, 2022). "One of the kidney-specific genes, KCNJ1 (potassium channel, inwardly rectifying subfamily J, member 1), is required for maintaining potassium balance, which has recently been shown to have low-expression in tumor proliferation and metastasis." (PMID 28036280, 2017). "The following marker genes were differentially expressed in the triphasic tumours relative to the blastemal tumours: PA (LHX1), RV/CSB/SSB (BMP2, CDH6, JAG1, PAPSS2), ePT and/or imHL (CIDEB, CLIC6, UNC5CL, VDR), and early DT/imHL (KCNJ1)." (PMID 29040332, 2017).
cancer (3 papers, 2013 to 2021). A tumor composed of atypical neoplastic, often pleomorphic cells that invade other tissues. "Remarkably, with the exception of potassium channel KCNJ1, all the other genes have already been implicated, in some way or another, in several types of cancer, as described in the Results section." (PMID 24194935, 2013). "This selection was mainly in view of the pivotal role of these genes in renal function (KCNJ1), cancer (SFRP1) and cell differentiation (TCF21)." (PMID 24194935, 2013).
kidney disease (3 papers, 2022 to 2024). "In this study, 248 genes associated with hereditary kidney diseases were all included in the panel, and no other suspicious gene mutations were found except KCNJ1 gene." (PMID 35761198, 2022).
KCNJ1 also shares sentences with these, for which no sentence is quoted: Gordon syndrome (3 papers); Hypomagnesemia (3); renal failure (3); Alkalosis (2); channelopathies (2); Dent disease (2); dyslipidemia (2); genetic disorders (2); heart defects (2); hyperaldosteronism (2); renal tubular disease (2); alcohol abuse (1); allergies (1); Alzheimer disease (1); Andersen-Tawil syndrome (1); Anxiety (1); Arrhythmia (1); asthma (1); astrocytomas (1); autism (1); autosomal dominant tubulointerstitial kidney disease (1); bladder cancer (1); cardiac hypertrophy (1); cardiovascular disease (1); chronic kidney disease (1); colitis (1); cystinuria (1); depression (1); electrolyte imbalance (1); hyperuricemia (1).
A further 30 diseases each share a sentence with KCNJ1 in 1 paper.